S100A8 (S100 calcium binding protein A8)
Diseases named in the same sentence as S100A8 in open-access papers (continued):
Sharing a sentence is not in itself a finding about the gene and the disease.
tumor (continued). "We previously identified S100A8 as one of the upregulated genes in the lungs of tumor-bearing mice." (PMID 36932197, 2023). "However, patients with tumors with ≥ 10% S100A8 + tumor epithelial cells did have significantly poorer survival (p < 0.001)." (PMID 37450087, 2023). "Tumors with S100A8 + tumor epithelial cells were found among all molecular subtypes." (PMID 37450087, 2023). "In addition, comparing the expression of S100A8 in tumor cells and immune cells at different stages can help determine the clinicopathological features and clinical outcomes of patients." (PMID 37701037, 2023). "The receptor for advanced glycation endproducts (RAGE) and its two dominant ligands S100A8/A9 and high mobility group box protein 1 (HMGB1) have been implicated as regulatory elements promoting tumor progression in hundreds of studies in both human and mouse systems." (PMID 36831371, 2023). "S100A8/A9 can promote tumor cell proliferation, invasion and metastasis, and its expression may be a potential prognostic factor of NSCLC patients." (PMID 36874092, 2023). "The distinct roles of S100A8/A9 in tumor proliferation might be consistent with its concentration and the tumor cell environment." (PMID 37701037, 2023). "Furthermore, S100A8 and S100A9 can activate inflammatory cells through neutrophil chemotaxis and are strongly associated with various tumor diseases." (PMID 37580334, 2023). "believed that S100A8 had therapeutic potential to interfere with tumor metastasis." (PMID 37124724, 2023). "S100A8/A9 are overexpressed in the tumor microenvironment (TME) of many solid tumors and are present in tumor cells, infiltrating host cells including leukocytes, and plasma of cancer patients, where their expression level positively correlates with tumor progression and metastasis." (PMID 36831371, 2023). "More recently, we found that Eritoran inhibited tumor growth through immunomodulation and vascular normalization, and that the carboxyl-terminal sequences of mouse S100A8 were necessary for binding to the mouse TLR4/MD-2 complex using a binding assay and CyClus docking simulation." (PMID 36932197, 2023). "Neither was the presence of ≥ 10 S100A8 + PMN cells in the tumor associated with significantly different patient prognosis." (PMID 37450087, 2023). "In view of the facilitation of drug resistance by S100A8/A9, S100A8/A9 antagonists might be developed to increase the vulnerability of tumor cells to chemotherapy, and the combined use of autophagy inhibitors might have excellent therapeutic effects." (PMID 37701037, 2023). "Therefore, we assessed the relative mRNA and protein levels of S100A8/A9 in the patients’ tumor tissues and found that S100A8/A9 levels were significantly higher in the tumor tissues." (PMID 37629174, 2023). "Furthermore, S100A8-treated macrophages cannot promote T cell proliferation in vitro and can suppress the cytotoxic function of tumor-primed T cells in vivo through PD-L1." (PMID 37701037, 2023). "S100A8 + staining in ≥ 1% of tumor cells was observed in 78/498 (16%) of cases." (PMID 37450087, 2023). "The abundance of cell-cell interactions in Mast cells, CD4 T cells, S100A8+ macrophage, and tumor cells compared to other cells was higher in responders than in non-responders, which indicated that there was more communication between these cell types in the responders." (PMID 37152010, 2023). "We also identify specific subtypes of stromal and immune cells critical to the formation of the pro-tumor microenvironment in metastatic lesions, including RGS5+ cancer-associated fibroblasts, CCL18+ lipid-associated macrophages, S100A8+ neutrophils and FOXP3+ regulatory T cells." (PMID 37612267, 2023). "This may be in part due to a multifaceted role of CXCL1 and S100A8/A9 secreted by LL2/B3a tumors in promoting tumor cell proliferation and survival." (PMID 37279067, 2023). "On the other hand, S100A8/A9 exerts significant effects on the tumor microenvironment." (PMID 38093319, 2023).
tumor (continued). "We observed that women in the group with the largest proportion of S100A8 + tumor epithelial cells had a mean age at diagnosis of 79.9 years, 4 years higher than the mean age at diagnosis of the study population, and that this group had a worse prognosis even after adjusting for age." (PMID 37450087, 2023). "Despite the endless emergence of drugs targeting S100A8/A9 and its receptors, which substantially inhibit different characteristics of tumor cells, they are only at the level of theoretical research, regrettably, there are no drugs that can be applied in practical life." (PMID 37701037, 2023). "S100A8/A9 induces the accumulation of MDSCs and is secreted by MDSCs and tumor cells, which forms a positive autocrine feedback loop within the inflammatory tumor environment." (PMID 36982351, 2023). "Our findings that SERPINB3 modulated the crosstalk between immune cells and cancer cells via secretion of CXCL1/8 and S100A8/A9 implicate this protease inhibitor member of the SERPIN superfamily in a key tumor strategy of evading antitumor immune responses and resisting therapies such as radiation." (PMID 37279067, 2023). "In addition, S100A8/A9 have been shown to modulate tumor growth and metastasis in colon and breast cancers." (PMID 37629174, 2023). "On the contrary, S100A8/A9 plays tumor suppressors in some types of cancers." (PMID 38093319, 2023). "Although the precise roles of S100A8/A9 in cancer remain a subject of debate, an increasing body of research suggests that S100A8/A9 may promote cancer progression by activating oncogenic signaling pathways and influencing the tumor immune microenvironment." (PMID 38093319, 2023). "Hepatocytes only weakly express these isoforms but immune cells producing abnormal levels of S100A8/A9 in the tumor microenvironment may deeply affect tumor initiation and progression." (PMID 36232334, 2022). "Higher concentrations of the S100/calgranulins were detected in dogs with inflammatory or neoplastic urinary tract diseases than in healthy dogs, and the S100A8/A9-to-S100A12 ratio was significantly lower in dogs with inflammatory conditions compared to those with neoplastic disease or health." (PMID 36411489, 2022). "Evidence from pre-clinical and clinical investigation have established S100A8 and its cognate-binding partner S100A9 as a potential prognostic biomarkers for reactivation of dormant tumor cells, prediction of metastatic risk and therapeutic responses failure in several malignancies, including BC." (PMID 35655319, 2022). "We anticipate that the therapeutic modulation of S100A8 activity in many tumor types might be a realistic clinical approach based on the results obtained." (PMID 35646116, 2022). "In addition to the expression of S100A8 and S100A9 by the tumor cells themselves, a remarkable influx of S100A8+S100A9+ immune cells was detected." (PMID 36303837, 2022). "It has been reported that extracellular S100A8/A9 proteins secreted by myeloid-derived suppressor cells promote leukocyte recruitment, angiogenesis, tumor migration, and formation of pre-metastatic niches in distal metastatic organs through activation of the MAPK and NF-κB signaling pathways." (PMID 35936690, 2022). "In addition to the induction of S100A8 in the premetastatic lung, upregulation of S100A8 in the tumor microenvironment, which involves into the recruitment of myeloid cells in lungs from the bone marrow to primary tumors." (PMID 35780158, 2022). "Several studies have concluded that S100A8/A9 could be released by tumor cell necrosis following hypoxia within growing tumors." (PMID 35610567, 2022). "Considering that the interaction between S100 Ca2+-binding proteins and RAGE promotes tumor progression also stimulating invasive effects, we next aimed to explore whether S100A8/A9-RAGE activation prompts the migration of TNBC cells." (PMID 35655319, 2022).
tumor (continued). "First, the association between S100A8 and clinical factors was explored, and no significant changes in age, gender, or tumor stage were found in the majority of cancer types, supporting prior findings." (PMID 35646116, 2022). "miR-24 by targeted silencing of the S100A8 gene could act as a tumor-suppressing gene and increase chemotherapy sensitivity of EC cells to paclitaxel." (PMID 35317077, 2022). "S100A8 may be a reliable biomarker for tumor prognosis and a viable prospective therapeutic target for human cancer immunotherapy (e.g., GBM, KIRC, LGG, and LIHC)." (PMID 35646116, 2022). "We previously identified S100A8 which was upregulated in the lungs of tumor-bearing mice." (PMID 35780158, 2022). "The detection in the blood of S100A8/S100A9 released by neutrophils in the tumour microenvironment suggests they could be utilised as a serum biomarker for diagnosis or prognosis of CA." (PMID 35842572, 2022). "In conclusion, our study revealed for the first time that intranasal S100A8 administration to lungs of mice had anti-inflammatory activities, which delayed cancer growth by altering the tumor microenvironment to deplete MDSC and modulate the oxidative balance to encourage accumulation of T cells." (PMID 35655772, 2022). "To test this hypothesis, we first investigated the expression of S100a9 and its partner, S100a8, in different cell subpopulations in the mammary gland, different developmental stages, and in tumor tissues." (PMID 35304461, 2022). "It has been reported that MDSC-derived Exos polarized macrophages to a phenotype that promoted tumor progression, and possessed S100A8/A9 chemotactic activity, which suggested that MDSC shed exosomes, which functioned as communicators in the tumor microenvironment." (PMID 35918733, 2022). "Similarly, S100A8 and S100A9 are also linked to anticancer properties, tumor progression, and the development of tumor metastasis." (PMID 35805957, 2022). "S100A8 expression in tumor cells (TCs) and immune cells (ICs) was assessed by immunohistochemistry, and its association with clinicopathologic features and infiltration of other IC subsets including CD4+, CD8+, and FOXP3+ tumor-infiltrating lymphocytes (TILs) and PD-L1+ ICs was evaluated." (PMID 33146829, 2021). "And inhibitor of S100A8/9 might be a suitable candidate for a combined therapy with ICI agents in tumor treatment." (PMID 34689842, 2021). "S100A8 is a potent amplifier of cancer development and tumor spread." (PMID 33466593, 2021). "S100A8 can be expressed in both immune cells (ICs) and tumor cells (TCs)." (PMID 33146829, 2021). "Tumor-induced upregulation of the myeloid-related protein S100A8 and S100A9, which also can be produced by MDSCs, inhibit DCs differentiation from hematopoietic progenitor cells (HPCs) via persistent upregulation of ROS in progenitor cells and induced accumulation of MDSCs." (PMID 35003065, 2021). "Once secreted in the extracellular space, S100A8/A9 are able to recruit further neutrophils and tumor cells to inflammatory and metastatic sites, and to sustain inflammatory conditions, promoting tumor development, and creating a favorable environment for metastatic niche formation." (PMID 34201758, 2021). "In addition, tumor infiltrating MDSCs have the ability to secrete S100A8/A9, which creates an autocrine positive feedback loop allowing for their own accumulation resulting in enhanced survival of cancer cells." (PMID 34201758, 2021). "In that context, S100A8/A9 may serve as a useful target for anti-metastasis therapy by suppressing the invasive and migratory capabilities of tumor cells, such as anti-S100A8/A9 monoclonal antibody." (PMID 33567747, 2021). "Elevated levels of S100A8/A9 have been found within tumor cells and various human cancers." (PMID 33567747, 2021). "High expression of S100A8 and S100A9 is strongly linked to tumor promotion." (PMID 34148033, 2021).
tumor (continued). "TIMP3+M3 and S100A8+N3 were both identified as protumoral cell types and related with lymph node metastasis, suggesting that those cells might promote the tumor progression in synergy." (PMID 34659209, 2021). "We can hypothesize that S100A8 plays a prominent regulatory role in tumor biology in comparison with S100A9, yet a larger study could identify more relationships and differences in S100A9 as well." (PMID 33466593, 2021). "In the context of cancer, S100A8 may facilitate the homing of tumor cells to the premetastatic niche." (PMID 34337026, 2021). "Immune signature genes, such as S100A8, had been shown to be pro-tumorigenic by inducing infiltration of myeloid derived suppressor cells (MDSCs) or suppressing T cell function at the tumor site." (PMID 33816228, 2021). "The primary receptor of S100A8/A9 on the tumor cells is RAGE." (PMID 33117687, 2020). "Additionally, S100A7, S100A8, and S100A9 recruit tumor-associated macrophages (TAM) to promote a microenvironment for immune evasion." (PMID 32728097, 2020). "Furthermore, by upregulating S100A8/A9 expression in tumor cells, tumor-infiltrating macrophages can promote tumor invasion and migration." (PMID 33288848, 2020). "Furthermore, these Gr1+ cells exhibited marked enrichment for suppressive myeloid genes, including Arg1, INOS, NOX2, and S100A8, compared with initial tumor dissociates or Gr1-depleted dissociates." (PMID 32634121, 2020). "Recently, it was reported that MDSC and S100A8/A9, co‐expressed members of the S100 family of calcium‐binding proteins that have an immunoregulatory role, can operate through a positive feedback loop to promote tumour development and metastasis." (PMID 33094923, 2020). "Furthermore, MDSCs also express and secret S100A8/A9, thus forming a positive feedback loop that helps to maintain suppressive MDSCs in the tumor microenvironment." (PMID 32793192, 2020). "It was also reported that CXCL1 could attract CD11b+ Gr1+ myeloid cells into the tumor, resulting in the production of chemokines including S100A8/9 that enhancing tumor growth and metastasis." (PMID 32213179, 2020). "In support of visual inspection of the images, striking differences could be seen between the healthy stroma and tumor regions at 10829 Da and 13146 Da, which correspond to S100A8 and S100A9, respectively." (PMID 32733643, 2020). "Moreover, in an in vitro experiment, MDSC isolated from the PALNs of ME180-GCSF cell-derived tumor-bearing mice expressed high levels of S100a8 and S100a9 mRNA." (PMID 32170086, 2020). "Moreover, S100A8/A9 was particularly valuable for patients presenting with normal levels of LDH indicating low tumor burden." (PMID 31806053, 2019). "Hence, rising serum levels of S100A8/A9 are likely to precede bulky tumor growth which finally leads to increases of S100B or LDH." (PMID 31806053, 2019). "Thus, we found that tumor S100A8 and S100A9 transcript levels as independent poor prognosticators in GBM." (PMID 30808902, 2019). "It has been shown that the inhibition of S100A8 and 9 in cancer cells resulted in abrogated tumor cell invasion and migration, and led to the subsequent down-regulation of matrix-metalloproteinase (MMP) 2, 9 which further emphasizes the implication of S100A8 and 9 in tumor invasion." (PMID 31528166, 2019). "Notably, HPK1 KD mice showed markedly increased pro-inflammatory pathways in response to priming with tumor antigens as shown by the enhanced related gene expression, e.g. S100A8, GZMB, NKp44, CXCL14, CX3CL1, CD1d2, KLRG1, CD11c, NLRP3 and MUC1." (PMID 30913212, 2019). "In addition, CCL2, secreted by primary tumor cells, stimulates lung ECs to release S100A8 and S100A9, leading to paracrine upregulation of SAA3, and consequently the formation of the premetastatic niche." (PMID 30654796, 2019). "Furthermore, data from the online database Oncomine demonstrated that S100A8 expression increased as the tumor stage increased." (PMID 30456203, 2018).
tumor (continued). "The authors proposed S100A8/A9 as a potent imaging biomarker for tumor-mediated immune remodeling." (PMID 29607329, 2018). "As expected, the CK7 positive cells (tumor cells) were also positive for S100A8." (PMID 30456203, 2018). "Secreted S100A8/S100A9 proteins have also been implicated in cancer growth and in the establishment of a favourable environment for metastasis by promoting the migration of monocytes and tumor cells to metastatic sites." (PMID 30558665, 2018). "Importantly, if the original IRISOE TNBC tumor cells CM was from hypoxic cells it further induced S100A8 secretion from THP1-macrophages." (PMID 29262555, 2017). "Indeed, estrogen induces neutrophil expression of a plethora of genes encoding protumoral cytokines/chemokines(e.g. CXCL1, CXCL2, S100A8, S100A9), matrix metalloproteinases(MMP3, MMP9) and COX-2 that are all known to promote tumor growth and metastasis." (PMID 28429725, 2017). "IL-6 and IL-8 released from myofibroblasts could also trigger the upregulation of S100A8/A9 in tumor-infiltrated myeloid cells." (PMID 29379499, 2017). "Indeed, the numbers of MMP9+ Ly6G+cells and S100A8+ Ly6G+ cells in the primary tumor and in the lung were significantly decreased by WCE treatment." (PMID 29142311, 2017). "Furthermore, S100A8/A9 induces apoptosis and autophagy in various cell types such as lymphocytes, macrophages, endothelial cells, and tumor cells." (PMID 29379499, 2017). "Immune cell alterations at the tumor site, and in nearby and distant organs, appear to depend on tumor-derived and immunomodulatory molecules, including GM-CSF, S100A8/A9 heterocomplex and chemokines, which target the Ras/MAPK, Jak/Stat, PI3K and TGFβ pathways." (PMID 29156694, 2017). "Moreover, a correlation with conventional tumor grading and serum markers for tumor development would foster the clinical use of S100A8/A9 as a marker for patient stratification and a prognostic potential as indicated by our results." (PMID 28744322, 2017). "Moreover, WCE significantly downregulated STAT3/S100A8 signaling, limited the expansion of MDSCs, and targeted the release of downstream chemokines from cancer cells, which prevented the tumor microenvironment entering a vicious cycle." (PMID 29142311, 2017). "Low concentrations of S100A8/9 stimulate tumour cell migration." (PMID 26880885, 2016). "Effect of calprotectin towards the tumour cells is dependent on the concentration: at high concentrations, heterocomplex of S100A8/9 exerts an apoptotic effect on colon carcinoma cell lines, but at the low concentrations, tumour cell growth is promoted by calprotectin." (PMID 26880885, 2016). "To learn whether S100A8/A9 might affect cellular migration, we performed an in vitro tumor migration assay." (PMID 26883112, 2016). "Therefore, tumour-cell-derived S100a8/a9 proteins are likely to signal in both autocrine and paracrine ways in these tumours." (PMID 25633981, 2015). "The mechanism of Mo-MDSC generation is relatively unknown although tumor-derived factors (e.g. prostaglandins, growth factors, cytokines or pro-inflammatory factors such as S100A8/A9) may induce Mo-MDSC generation." (PMID 25992611, 2015). "Let-7 had a confirmed decreasing expression in tumor tissues, while S100A8 level was upregulated." (PMID 25673070, 2015). "In this study, in order to further exploit tumor stoma interactions, we first verified whether tumor cells release soluble mediators able to fragment the S100A8 protein." (PMID 24670043, 2014). "In addition, we found an association between low S100A8 levels (mRNA levels in Cohort II and protein levels in Cohort III) and tumor differentiation." (PMID 24885002, 2014). "Therefore, the analyses conducted on the expression of these proteins and tumor behavior suggest that S100A8/A9 can become potential therapeutic targets in cancer treatment." (PMID 25371673, 2014).